FCER1G (Fc epsilon receptor Ig)
Diseases named in the same sentence as FCER1G in open-access papers (continued):
Sharing a sentence is not in itself a finding about the gene and the disease.
multiple myeloma (3 papers, 2020 to 2023). "Combined with GO and KEGG analysis results above, FCER1G might interact with other MM associated genes and was mainly involved in leukocyte migration, cell chemotaxis, and immune and inflammatory response pathway, and therefore exerted an anti-cancer effect in multiple myeloma." (PMID 31956364, 2020). "In order to understand the expression of FCER1G in MM patients and other different myeloma stages, we employed six datasets to analyze the expression level of it." (PMID 31956364, 2020). "However, in another study the expression level of Fcer1g negatively correlated with myeloma progression, and high Fcer1g expression was suggested as a favorable biomarker in multiple myeloma patients." (PMID 38017015, 2023). "Downregulation of FCER1G expression was closely related to the deterioration of myeloma." (PMID 31956364, 2020). "In summary, the expression of FCER1G decreased with the evolution of monoclonal gammopathy, suggesting that FCER1G might be involved in the malignant progression of myeloma." (PMID 31956364, 2020). "However, in this research, the exact pathophysiologic role of FCER1G in myeloma cells was not been fully demonstrated." (PMID 31956364, 2020).
anaphylaxis (2 papers, 2011 to 2023). An acute hypersensitivity reaction that occurs from exposure to an allergen. "Function of the high-affinity IgE receptor (FCER1G) is associated with anaphylaxis." (PMID 37907783, 2023).
fibrosis (2 papers, 2014 to 2022). the formation of excess fibrous connective tissue in an organ or tissue in a reparative or reactive process. "Among these genes, the expression of inflammation-associated FCER1G, OSM, VEGFA, and ZAP70 was lower in high-grade fibrosis than in low-grade fibrosis, whereas CHIT1 expression, which is associated with fibrogenic activity of macrophages, was higher in high-grade fibrosis." (PMID 35052861, 2022).
periodontitis (2 papers, 2022 to 2025). An acute or chronic inflammatory process that affects the tissues that surround and support the teeth. "These are located at the genes SIGLEC5, DEFA1A3 and FCER1G, and those are associated with periodontitis at a genome‐wide significance level." (PMID 40197750, 2025). "Currently, the available dataset for GWAS related to early onset (grade C) periodontitis identified potentially predisposing variants in the genes of DEFA1A3, FCER1G and SIGLEC5 at the level of genome‐wide significance." (PMID 40197750, 2025).
renal carcinoma (2 papers, 2023 to 2024). A carcinoma arising from the epithelium of the renal parenchyma or the renal pelvis. "In addition, FCER1G has been linked to macrophage and T cell function in renal cancer." (PMID 38817876, 2024). "In renal cancer, the high expression of FCER1G may be a functional basis for the induction of M2 macrophages by the increased secretion of IL-4." (PMID 36778919, 2023).
acute myocardial infarction (1 paper, 2022). Necrosis of the myocardium, as a result of interruption of the blood supply to the area. "A higher expression level of FCER1G has also been observed in patients with acute myocardial infarction." (PMID 36012903, 2022).
allergic asthma (1 paper, 2022). A asthma with a basis in a pathological type I hypersensitivity reaction. "Top immune gene weight was linked to Fc Fragment Of IgE Receptor Ig (FCER1G) expression, a receptor for immunoglobulin E (IgE) and a key factor in the pathogenesis of allergic asthma." (PMID 35189979, 2022).
bladder cancer (1 paper, 2022). "In the case of bladder cancer, bioinformatic analysis revealed that FCER1G is a potential key immunoregulator in the microenvironment of bladder cancer." (PMID 36131933, 2022).
Cirrhosis (1 paper, 2020). A chronic disorder of the liver in which liver tissue becomes scarred and is partially replaced by regenerative nodules and fibrotic tissue resulting in loss of liver function. "Upregulation of the downstream signaling in experimental cirrhosis and ACLF were confirmed by qPCR for Fcer1g and Nfkb1." (PMID 32733451, 2020).
depression (1 paper, 2026). "Our results displayed that the mRNA levels of Fcer1g, Fcer1a, and Fcgr4 were all upregulated in the brains of LPS‐induced depression model mice, which were all down‐regulated by DSCG administration." (PMID 41556446, 2026).
head and neck squamous cell carcinoma (1 paper, 2019). A squamous cell carcinoma that arises from any of the following anatomic sites: lip and oral cavity, nasal cavity, paranasal sinuses, pharynx, larynx, and salivary glands. "Interestingly, all five of these genes, CD74, C1QB, FCER1G, TYROBP, and C1QA are part of a protein-protein interaction network comprised of 20 proteins in total that are found only in head and neck squamous cell carcinomas but not in normal head and neck specimens." (PMID 31139325, 2019).
liver cancer (1 paper, 2023). An epithelial or non-epithelial malignant neoplasm that arises from the liver. "The results demonstrated that the expression of FCER1G, PFN1, ACTG1, PABPC1, CALM1, and RPS8 was significantly upregulated in the liver cancer cells, whereas KLRB1, LDB2, and FYN exhibited the opposite trend." (PMID 37397471, 2023).
metastasis (1 paper, 2020). The spread or migration of cancer cells from one part of the body (where they first appeared) to another. "Moreover, expression of individual genes in this panel, including IL18RAP, CXCL11, FCER1G, CSF3R and IL2RG were strongly linked to distant metastasis, lymph node metastasis, tumor stage, clinical stage or pathologic grade." (PMID 33049716, 2020).
nasal polyps (1 paper, 2022). "FCER1G which encodes the gamma chain of high-affinity IgE receptor (FcεRI), was primarily expressed by mast cells in nasal polyp tissues." (PMID 36466903, 2022).
Obesity (1 paper, 2021). Accumulation of substantial excess body fat. "Notably, FCER1G, LYN and SYK downregulation were able to reduce obesity induced by high-fat diet and the growth of lipid droplets in adipocytes." (PMID 34506234, 2021).
ovarian carcinoma (1 paper, 2026). A malignant neoplasm originating from the surface ovarian epithelium. "Notably, eight proteins upregulated in the invasive stroma (NNMT, FCGR1A, FCER1G, TYMP, F13A1, DCK, CASP3, and SYK) represented FDA-approved drug targets outside of ovarian cancer, emphasizing their high relevance for future preclinical investigations." (PMID 41233595, 2026).
parasitemia (1 paper, 2024). "We also show significant expression of FCER1G in B cells, Mono, and DC in patients, which is induced by IFN-γ and encodes for a gamma chain of the FC receptor and it is suggested to play an important role in controlling parasitemia." (PMID 39830896, 2024).
pilocytic astrocytoma (1 paper, 2020). Pilocytic astrocytoma is a rare subtype of low-grade glioma of the central nervous system characterized by a well circumscribed, often cystic, brain tumor with a discrete mural nodule and long, hair-like projections that extend from the neoplastic astrocytes. "Although research has reported that FCER1G genes are expressed at higher levels in pilocytic astrocytomas than in LGG, there are no reports of FCER1G expression levels in LGG and SKCM." (PMID 32903590, 2020).
prostate carcinoma (1 paper, 2021). A carcinoma that arises from epithelial cells of the prostate gland. "Further, FCER1G is crucial in the prognosis of prostate cancer." (PMID 34257539, 2021).
renal fibrosis (1 paper, 2022). A final common manifestation of a wide variety of chronic kidney diseases characterized by glomerulosclerosis and tubulointerstitial fibrosis. "Combined with the findings of the current research, it is suggested that Fcer1g has a close relationship with the progress of renal fibrosis and is a potential target for CKD treatment." (PMID 36523757, 2022).
Splenomegaly (1 paper, 2023). Abnormal increased size of the spleen. "Finally, we generated Slc29a3−/− mice lacking both FcRγ and DAP10 (Slc29a3−/−Hcst−/−Fcer1g−/− mice), in which splenomegaly did not develop and splenic monocyte proliferation was reduced to the level of splenic monocytes of the WT mice." (PMID 37462944, 2023).
triple-negative breast carcinoma (1 paper, 2025). An invasive breast carcinoma which is negative for expression of estrogen receptor (ER), progesterone receptor (PR), and human epidermal growth factor receptor 2 (HER2). "This list was further filtered through a triple-negative breast cancer (TNBC) scRNA-Seq dataset by applying a stringent criteria selection (i.e., high expression restricted to the macrophage cluster), leading to 4 genes: SPP1, APOC1, FCER1G, and MMP9." (PMID 39808498, 2025).
valvular heart disease (1 paper, 2022). "Although some IUGR rats were given a normal protein diet after birth to achieve normal body weight and nutritional status, the possibility of valvular heart disease in these rats was increased due to the upregulated expression of Fcer1g, leading to increased production and secretion of serotonin." (PMID 35938117, 2022).
Wiskott-Aldrich syndrome (1 paper, 2017). Wiskott-Aldrich syndrome (WAS) is a primary immunodeficiency disease characterized by microthrombocytopenia, eczema, infections and an increased risk for autoimmune manifestations and malignancies. "These genes, namely, Complement C1q A Chain (C1QA), Fc Fragment Of IgE Receptor Ig (FCER1G) Vav Guanine Nucleotide Exchange Factor 1 (VAV1) and Wiskott-Aldrich Syndrome (WAS) were all confirmed to be significantly upregulated." (PMID 29232382, 2017).
tumor (56 papers, 2010 to 2026). "It has been reported that metastasis-associated gene FCER1G was abundantly expressed in circulating tumor cells (CTCs) of a PCa patient who was sensitive to docetaxel, a chemotherapy agent." (PMID 38017548, 2023). "As subset 2, the aging- specific subset, expresses high levels of granzymes and Fcer1g, they may have cytotoxic potential in tumor immunity with an increased risk of developing tumors with age." (PMID 38327516, 2024). "Additionally, a high expression of FCER1G in ccRCC is closely linked to infiltration of the tumor microenvironment, which inhibits T cell proliferation and activation." (PMID 37065178, 2023). "This is urgently needed, as it may provide insight into the underlying mechanism of FCER1G expression interaction with tumor immunity and affect the prognosis of ccRCC." (PMID 35120484, 2022). "However, the role of FCER1G in tumor progression and underlying molecular mechanisms are poorly understood." (PMID 33579299, 2021). "Interestingly, expression of Fcer1g which encodes for the Fc Epsilon Receptor Ig protein (FCER1G), was differentially expressed within the αβILTCK cluster compared to other tumour infiltrating CD8+ T cells, including PD-1+ T cells, regardless of their activation status." (PMID 35768418, 2022). "A significant positive correlation was also identified between expression of Fcer1g and the infiltration levels immune cells using the immune infiltration analysis, implicating the role of this gene in regulating tumor immunology in endometrial cancer." (PMID 38017015, 2023). "FCER1G expression was positively associated with tumor prognostic outcome, growth, and migration; also, FCER1G was closely related to tumor immunity and tumor microenvironment (TME)." (PMID 37071001, 2023). "Among these results, a high expression of FCER1G was related to the high T and N stages—namely, the proliferation and migration of tumor cells." (PMID 35204406, 2022). "Among these potential target genes, the expression of FCER1G was related to clinical relevance, such as the tumor invasion stage, tumor nodal stage, and primary tumor location." (PMID 35204406, 2022). "Moreover, these FCER1G+ T cells were enriched in cancerous compared to adjacent normal tissue, indicating that FCER1G is a lineage-defining marker that characterises tumour infiltrating T cells committed to the αβILTCK lineage." (PMID 35768418, 2022). "Moreover, SRGN, S100A11, and FCER1G contribute to the identification of mast cells in tumor microenvironments." (PMID 34575089, 2021). "FCER1G, known as FcRγ, is a key molecule involved in tumor progression." (PMID 33579299, 2021). "Hence, tumour-specific FCER1G and PECAM1 may represent bona fide therapeutic targets that warrant further evaluation." (PMID 29784888, 2018). "Our proteomic analysis, based on data from the Clinical Proteomic Tumor Analysis Consortium (CPTAC), focused on CCL5, IL18, and FCER1G." (PMID 41155216, 2025). "Single-cell RNA-seq of PyMT tumor CD8+ T cells revealed unique signatures for early effectors (Il7r, Tcf7), exhausted (Pdcd1, Tox), and ILTCKs (GzmB, Klrb1c, Fcer1g)." (PMID 37892995, 2023). "We only retained myeloid cells in clusters 12, 14, and 20 and removed tumor cells in cluster 12 according to examine the expression of CD14 and FCER1G genes." (PMID 35493068, 2022). "Non-tumor components included endothelial cells (expressing VWF, CDH5, ECSCR, SLCO2A1, and MYCT1), pericytes (marked by RGS5, MCAM, and PDGFRB), normal oligodendrocytes (showing PTGDS, MBP, TF, and MOG expression), and TAMs (identified by CD14, AIF1, FCER1G, FCGR3A, TYROBP, and CSF1R)." (PMID 41394801, 2025). "Correlative elaboration of key molecules including FCER1G, ZGMM, KIR2DL4, KIR3DH5, KLRC1, KLRB1, and FKBP5 among the 5 cell‐type clusters in evolutionary development trajectory of NKT for immune escalation against evasion of vital tumor cells and mutants was further illustrated by Violin plots." (PMID 37693048, 2023).
cancer (21 papers, 2017 to 2026). A tumor composed of atypical neoplastic, often pleomorphic cells that invade other tissues. "Using The Cancer Genome Atlas dataset, a 5-CD8Gs risk model (KLRB1, FYN, IL2RG, FCER1G, and DGKZ) was constructed, which was verified in International Cancer Genome Consortium and gene expression omnibus datasets." (PMID 38489709, 2024). "Combined with previous eQTL analyses, we found nine eQTLs, including nine eVariants and two eGenes (HGF and FCER1G), that correlated with the survival of cancer patients." (PMID 35204406, 2022). "Studies have shown that FCER1G participates in a variety of immune functions and can be used as a prognostic marker for a variety of cancers." (PMID 34195091, 2021). "Integration with publicly available single-cell sequencing data revealed that these proteins were mostly macrophage and monocyte-associated with malignant features (TYMP, FCER1G, FCGR1A, SYK, and F13A1), except NNMT, which was highest in cancer-associated fibroblasts (Table EV4)." (PMID 41233595, 2026). "Previous studies have confirmed the role of FCER1G in several cancers." (PMID 36900319, 2023). "The results of two pan-cancer studies suggest that FCER1G is involved in the immune infiltration process of tumors and may be a potential immunotherapeutic target." (PMID 37907783, 2023). "Furthermore, the transcriptional levels of FCER1G and SPI1 can also distinguish the OS patients into two clusters with different prognosis and immune cell infiltrations, suggesting a potential treatment target for OS and other TYROBP-associated cancers." (PMID 35078433, 2022). "SPI1, as the key transcription factor for the network, may shape a positive-feedback network with the signaling from TYROBP/FCER1G or environmental TNF-α/IFN-γ, then furtherly initiate the whole SPI1-TYROBP-FCER1G network to regulate the immune infiltration and cancer prognosis." (PMID 35078433, 2022). "Arginase (Arg1) is well-known for regulating cancer cell immune escape within the TME, and Fcer1g is a key gene involved in cancer immune infiltration." (PMID 40458726, 2025). "We explored them utilizing the pathway activity module of the GSCALite platform to determine whether these six genes (TYROBP, FCER1G, CD48, LST1, APOE, and APOC1) act through specific cancer pathways." (PMID 38515073, 2024). "In myeloid cells, the top 50 pan-cancer central genes included seven genes involved in myeloid cell differentiation (CD4, FCER1G, IRF8, TYROBP, TLR2, TREM2 and ITGAM), but only two of them (FCER1G and TYROBP) were found among the top 50 DEGs." (PMID 36350625, 2023). "Moreover, for FCER1G, LGALS9, TWEM149, EVI2B, and HAMP, the gene expression levels in the cancer population were higher than those in the normal population." (PMID 32903590, 2020).
infection (21 papers, 2008 to 2025). The state of being infected such as from the introduction of a foreign agent such as serum, vaccine, antigenic substance or organism. "Fc ε-receptor Ig (FCER1G) encodes a protein similar to the Fc fragment of γ-Ig and has a pivotal role in infection by activating the phagocytosis in myeloid cells and inducing an antineoplastic activity." (PMID 39273632, 2024). "The number of Ifnar–/– P14 cells, which are the main target of NK cells was vanished in Fcer1g+/– mice and partially rescued in Fcer1g–/– mice as compared to that of WT P14 transfer after infection with LCMV-Docile." (PMID 31220194, 2019). "On contrary, higher viral titers were found in lymphatic and extra lymphatic organs of Fcer1g-sufficient mice but almost resolved at long-term infection." (PMID 31220194, 2019). "Some genes related to the inflammatory response, such as Cxcl10, Clu and antigen presentation, such as B2m, Fcer1g showed over-expression only at 72 and 96 hr post infection." (PMID 18558011, 2008). "In addition inflammatory genes e.g., Fcer1g, and Mif were also over-expressed at 72 and 96 hr post infection." (PMID 18558011, 2008). "On day 6 and 9 upon infection, we found that the number of WT P14 cells was specifically reduced in Fcer1g+/– but not in Fcer1g–/– mice, indicating the robust expansion of virus-specific CD8+T cells in the mice that are devoid of FcRγ." (PMID 31220194, 2019).
neurological disease (1 paper, 2023). "Some genes, such as CD2AP, FCER1G, MAPK3, and EPHX2, were in nodes or core nodes of this neurological disease network, indicating that the CpG sites and these target genes may influence AD development." (PMID 38092781, 2023).
peripheral neuropathy (1 paper, 2024). A disorder affecting the peripheral nervous system. "Together, the regulation of FCER1G, SYK, and PTK2B on the development of nerve system disease suggests that they most likely contribute to T2DM‐induced peripheral neuropathy." (PMID 38018513, 2024).
FCER1G also shares sentences with these, for which no sentence is quoted: osteopetrosis (6 papers); lupus (5); childhood leukemia (4); acne (3); diabetic kidney disease (3); eczema (3); influenza (3); neurodegenerative disease (3); fungal infection (2); glomerulonephritis (2); HIV-1 infection (2); kidney diseases (2); non-small cell lung carcinoma (2); ZIKV infection (2); age (1); AIDS (1); allergic rhinitis (1); ANCA-associated vasculitis (1); arboviral disease (1); artery thrombosis (1); Autoimmunity (1); behavioral disorders (1); brain tumors (1); breast carcinoma (1); Burkitt lymphoma (1); cognitive decline (1); colon cancer (1); dengue disease (1); diabetes (1); endocarditis (1).
A further 39 diseases each share a sentence with FCER1G in 1 paper.